TFEB (transcription factor EB)
Diseases named in the same sentence as TFEB in open-access papers (continued):
Sharing a sentence is not in itself a finding about the gene and the disease.
neurodegenerative disease (continued). "Therefore, the induction of TFEB activity represents a potential therapeutic strategy for human neurodegenerative diseases." (PMID 35851059, 2022). "Efforts have been made to develop TFEB agonists to enhance autophagy in neurodegenerative disease, and our results suggest that TFE3 could also be a promising drug target." (PMID 34912803, 2021). "Hence, our aim was to investigate the effects of TFEB activation on NPCD, which is a fatal neurodegenerative disease characterized by the pathogenic accumulation of cholesterol in lysosomes." (PMID 33921734, 2021). "Recent studies showed that Tre could induce TFEB activation and reduce disease burden in a model of neurodegenerative disease." (PMID 31947943, 2020). "This inhibits the interaction of TFEB with Rag GTPases, and induces its nuclear translocation, thus inducing the expression of autophagy/lysosomal genes independently of mTORC1 (although its role in neurodegenerative diseases remains elusive)." (PMID 33224433, 2020). "Although TFEB is a promising therapeutic agent for the treatment of neurodegenerative diseases, it is likely that the proinflammatory features of TFEB might impede its clinical utilization." (PMID 33335764, 2020). "Transcription factor EB (TFEB)-based gene therapy is a promising therapeutic strategy in treating neurodegenerative diseases by promoting autophagy/lysosome-mediated degradation and clearance of misfolded proteins that contribute to the pathogenesis of these diseases." (PMID 33335764, 2020). "Numerous studies support the idea that impaired TFEB function may contribute to the pathogenesis of most degenerative diseases characterized by aberrant intracellular accumulation of macromolecules." (PMID 30889901, 2019). "Our data indicated that TFEB might play a key role in proteasome impairment-induced ALP activation in neurodegenerative diseases." (PMID 31508418, 2019). "Thus, our results suggest that TFEB is an effective, therapeutic target for neurodegenerative diseases due to its dual functions activating the Nrf2-ARE pathway as well as the autophagy pathway." (PMID 31586112, 2019). "Our data showed that short-term proteasome inhibition significantly activates TFEB-mediated ALP, which might explain the mechanism of TFEB/ALP activation concomitant with proteasome impairment at the early stage of neurodegenerative diseases." (PMID 31508418, 2019). "Moreover, the involvement of TFEB in most neurodegenerative diseases has been extensively documented." (PMID 30889901, 2019). "Finally, there is great interest in manipulation of the lysosomal system, for example through TFEB activation, to enhance clearance of protein aggregates that can lead to pathology for example in neurodegenerative disease." (PMID 30559339, 2018). "It is also possible that the pathways regulating TFEB export may provide therapeutic opportunities for regulation of TFEB in neurodegenerative disease." (PMID 29992949, 2018). "Understanding how to pharmacologically control TFEB activity is urgently needed to move the field forward and help set-up clinical studies to evaluate the efficacy of TFEB-mediated lysosomal enhancement in neurodegenerative disease." (PMID 28165011, 2017). "TFEB, as a critical transcription factor regulating lysosomal biogenesis and lysosomal degradative pathway, is demonstrated to be involved in the pathogenesis of neurodegenerative diseases." (PMID 27209302, 2016). "The C-ETS2-mediated TFEB-induction mechanism may play a central role in the response of neurons to oxidative stress during the early stages of neurodegenerative disease, thus revealing a new avenue of neuroprotective therapy in neurodegenerative diseases." (PMID 27195074, 2016). "Additionally, aging is a key factor for neurodegenerative disease, future studies dissecting the molecular connections between TFEB, aging, and neurodegenerative disease may provide novel insight into the discovery of agents for aging and NDs." (PMID 37191408, 2023).
neurodegenerative disease (continued). "Therefore, whether activation of TFEB by inhibiting or activating these key regulators affects other normal cellular functions needs to be considered and further examined in neurodegenerative diseases models." (PMID 36184826, 2023). "Therefore, either TFEB expression, or TRPML1/2 activation in conjunction with iron chelation, may be promising therapeutic approaches toward treating neurodegenerative diseases associated with iron dyshomeostasis." (PMID 36522443, 2022). "Dysregulation of TFEB activity, however, was reportedly contributed to the development of various diseases, including catabolic hyperactivity in tumors, accumulation of abnormal aggregates in neurodegenerative diseases, and aberrant host responses in inflammatory diseases." (PMID 34490237, 2021). "Therefore, TFEB is critically involved in the pathophysiological process of various neurodegenerative diseases as its key role in regulating lysosomal function, and maintaining TFEB activity can be considered as an effective way to accelerate the clearance of abnormally accumulated proteins." (PMID 34490237, 2021). "We further elaborated the involvement of TFEB dysregulation in the pathophysiological process of various diseases, such as the catabolic hyperactivity in tumors, the accumulation of abnormal aggregates in neurodegenerative diseases, and the aberrant host responses in inflammatory diseases." (PMID 34490237, 2021). "Thus, trehalose might be a suitable alternative therapeutic option for neurodegenerative diseases because of its ability to regulate TFEB expression and thus could help restore normal lysosomal function." (PMID 34970114, 2021). "Moreover, our results suggest that the novel, small TFEB might be a promising therapeutic target for neurodegenerative diseases." (PMID 34702966, 2021). "Therefore, the activity of TFEB could be regulated by an agonist or a specific inhibitor or kinase activator, making TFEB an attractive therapeutic target for neurodegenerative diseases." (PMID 34702966, 2021). "Therefore, promoting TFEB translocation into the nucleus to restore autophagy-lysosomal pathway function may be a potential treatment strategy for neurodegenerative diseases." (PMID 30706760, 2019). "Therefore, it is likely that misfolded protein in neurodegenerative diseases, like α-synuclein in PD and huntingtin in HD, might also possess the similar property in regulating TFEB expression and cellular distribution." (PMID 28769785, 2017). "Transcription factor EB (TFEB) is a positive regulator for the autophagy-lysosomal pathway and is impaired in developing neurodegenerative diseases, including AD." (PMID 38379403, 2025). "Trehalose is a natural disaccharide that induces autophagy via transcription factor EB (TFEB), and has gained interest for neuroprotective and anti-aggregant/protein clearance effects in models of neurodegenerative diseases." (PMID 41013508, 2025). "The crucial role of TFEB and its mediated ALP in the clearance of abnormal aggregates has been supported in several preclinical models of neurodegenerative diseases." (PMID 36184826, 2023). "Thus, it is necessary to in‐depth understanding of TFEB functions under various physiological and pathological conditions at the molecular, cellular, and functional levels to further clarify its roles in disease pathology and to inform the development of therapeutics for neurodegenerative diseases." (PMID 36184826, 2023). "Here, we show that zinc induced lysosomal biogenesis via TFEB activation and lysosomal acidification via increases in the assembly and expression of V-ATPase, which may ameliorate the accumulation of aggregated proteins in neurons of neurodegenerative diseases." (PMID 36246521, 2022).
neurodegenerative disease (continued). "Since the compounds like C1 analog control TFEB activity independently of mTORC1 (mechanistic target of rapamycin (serine/threonine kinase) which is known to regulate multiple cellular processes; therefore these C1 analogs could play an important role in the treatment of neurodegenerative diseases." (PMID 34970114, 2021). "c-Abl inhibition activates TFEB and promotes cellular clearance in a Niemann-Pick type C (NPC) models, a neurodegenerative disease characterized by cholesterol accumulation in lysosomes." (PMID 33316913, 2020). "Moreover, the broad applicability of TFEB and its role in the ALP make it an exceedingly attractive therapeutic target for treating neurodegenerative diseases." (PMID 36184826, 2023). "Importantly, TFEB has been previously proposed as a therapeutic target in ALS and other neurodegenerative disease." (PMID 33300868, 2020). "The activation of TFEB has been shown to stimulate ALP function, which enhances the clearance of misfolded or aggregation-prone proteins both in cellular models of protein misfolding and mouse models of neurodegenerative disease." (PMID 31297061, 2019). "Transcription factor EB (TFEB) is a basic helix–loop–helix–leucine–zipper transcription factor, which is considered the main regulator of lysosomal biogenesis and autophagy, and mediates various physiological processes, including immune response, neurodegenerative diseases, and metabolic diseases." (PMID 35392078, 2022). "Furthermore, trehalose facilitates the nuclear translocation of TFEB independent of mTORC1 activity, and its administration may reduce disease burden in a mouse model of a prototypical neurodegenerative disease." (PMID 39454957, 2024). "The evidence that CPZ affects TFEB localization through Rag GTPases prompts us to speculate that CPZ plays two roles in the regulation of autophagy, similar to our previous study which shows that autophagy dysfunction can be induced by dual effects in a neurodegenerative disease model." (PMID 37745295, 2023). "In the context of neurodegenerative disease due to impaired autophagy, this suggests that GSK3β may help to promote autophagy not only through the activation of ULK1, but also through preserving levels of transcription factors like TFEB that lead to the upregulation of autophagy-promoting genes." (PMID 37443837, 2023).
infection (55 papers, 2013 to 2026). The state of being infected such as from the introduction of a foreign agent such as serum, vaccine, antigenic substance or organism. "On the other hand, TFEB as well as TFE3 have been observed to be activated during infection and double-deficiency was consistently observed to yield smaller CCVs." (PMID 40435199, 2025). "The ability of TFEB to mitigate lipotoxicity in the context of pathogenic infection indicates that its role in host innate immunity emerges, in part, from its regulation of the cross‐talk between lysosomal function, lipid catabolism, and the immune response." (PMID 37728021, 2023). "We found that TFEB expression was reduced at an early point of infection in NCoR1-deficient conditions, indicating a crucial role of NCoR1 in TFEB functionality." (PMID 37590294, 2023). "Specifically, rapamycin and select rapalogs (everolimus and temsirolimus) promoted infection at the cell entry stage, and this was functionally linked to nuclear accumulation of TFEB and the lysosomal degradation of IFITM proteins by endosomal microautophagy." (PMID 36264642, 2022). "Specifically, rapamycin and select rapalogs (everolimus and temsirolimus) promote infection at the stage of cell entry, and this is functionally linked to nuclear accumulation of TFEB and the lysosomal degradation of IFITM proteins by endolysosomal microautophagy." (PMID 33880473, 2022). "Finally, we took advantage of TFEB-deficient cells to formally address the role that TFEB activation plays during rapalog-mediated enhancement of infection." (PMID 33880473, 2022). "Therefore, hlh-30/TFEB deletion completely suppressed the enhanced survival phenotypes of nhr-49/PPARA gain-of-function alleles, which is consistent with hlh-30/TFEB functioning downstream of nhr-49/PPARA for host infection survival." (PMID 33978570, 2021). "Evolutionarily, its role in host defense is conserved, as demonstrated by HLH-30, the TFEB ortholog in Caenorhabditis elegans, which orchestrates antimicrobial gene expression during infection." (PMID 41394849, 2025). "Expectedly, in organisms such as C. elegans that lack a cellular immune system, the worm ortholog of TFEB has been shown to orchestrate the predominant response to infection." (PMID 40465712, 2025). "LC3 and GABARAP lipidation also contribute to TFEB activation in response to kidney injury and pathogen infection." (PMID 40195022, 2025). "Recent evidence suggests that the noncanonical function of the ATG conjugation system is also involved in TFEB activation by other cellular stresses such as mitochondrial damage and pathogen infection." (PMID 40880129, 2025). "After expression in cells, we noted that the TFEB phosphomutant was resistant to degradation following OC43 infection and its persistent expression decreased viral load and enhanced cell viability." (PMID 40465712, 2025). "In this study, infection of TFEB- and TFE3-knockdown cells with IBV, HCoV-OC43 and PEDV showed down-regulation of the pro-apoptotic factor CHOP and autophagy-related gene SQSTM1." (PMID 41450945, 2025). "Mechanistically, HLH-30 drives most of the transcriptional host response, and both HLH-30/TFEB-regulated antibacterial and autophagy genes are required for host tolerance of infection." (PMID 40180610, 2025). "HLH-30/TFEB is activated early during infection and controls the expression of the transcriptional immune response to infection." (PMID 40180610, 2025). "This is a story out of Shakespeare, in which viruses betray a cellular ally in a manner worthy of Brutus; first usurping the function of TFEB, then cleaving that same protein when the needs of the virus change late in infection." (PMID 39398108, 2024). "Our findings identify the preferential distribution of TFEB in colonic epithelial cells, where TFEB can be activated by infection to enhance anti-bacterial peptide expression, holding promising implications for the advancement of anti-bacterial therapeutics." (PMID 38711975, 2024).
infection (continued). "In the early stages of infection, TFEB promotes EV-D68 RNA replication, between 0 h to 3 h post infection." (PMID 39398108, 2024). "For instance, in infections with Leishmania donovani, TFEB expression is upregulated, where it negatively affects critical immune functions such as antigen presentation and cytokine secretion." (PMID 39572689, 2024). "Further investigation uncovered that the infection-activated TFEB contributed to the augmentation of anti-bacterial peptide expression without affecting the intact structure of the colonic epithelium or inflammatory cytokine expression." (PMID 38711975, 2024). "We noted a progressive increase in nuclear localization of TFEB during the course of infection, with peak activation observed 24 h post-infection (hpi)." (PMID 39572689, 2024). "TFEB is required for early infection, but cleaved by a viral protease late in infection as part of a viral strategy to subvert the autophagy machinery to remodel membranes while inhibiting degradative autophagy." (PMID 39398108, 2024). "This is in agreement with the original CVB3 data, in which the newly cleaved (and inactive) TFEB translocates to the nucleus late during infection." (PMID 39398108, 2024). "Proteomics analysis reveals extensive TFEB co-immunoprecipitation with several mitochondrial proteins, whose interactions are disrupted upon infection with S. Typhimurium." (PMID 38263327, 2024). "In conclusion, this study elucidated the precise localization of TFEB within the colon and examined the interplay between infection and epithelium facilitated by TFEB." (PMID 38711975, 2024). "In this study, we present a molecular model elucidating how Plasmodium parasites activate the pro-survival transcription factor TFEB during liver stage infection." (PMID 39572689, 2024). "Second, we showed that induction of autophagy by amiodarone is required for infection control and that TFEB activation upon amiodarone treatment is enhanced." (PMID 38916320, 2024). "To further investigate the observed effects of amiodarone on infection control and autophagy induction, we focused on transcription factor EB (TFEB), a master regulator of autophagy and lysosomal biogenesis (30, 50, –, 53)." (PMID 38916320, 2024). "We also observed similar reduced levels of TFEB with increased infection in NCoR1MyeKO BMDMs as compared to control." (PMID 37590294, 2023). "In previous studies, we identified two main genetic pathways that promote the induction of an infection-specific gene expression signature that promotes host survival: the acetylcholine-Wnt pathway and the TFEB/HLH-30 pathway." (PMID 36860863, 2023). "To ascertain the role of TFEB in compromised autophagy and lysosomal biogenesis, we overexpressed the flag-tagged TFEB in NCoR1 KD mo-MΦ followed by H37Rv infection for 24 h." (PMID 37590294, 2023). "It is interesting to note that under both hunger and infection states, the transcription factor EB (TFEB) acts as a master regulator of lysosomal activities and autophagy." (PMID 38138088, 2023). "Previous studies demonstrated that C. elegans HLH-30/bHLH, a basic helix-loop-helix transcription factor orthologous to mammalian TFEB, plays an important role in longevity and host response to infection." (PMID 37928537, 2023). "Further cementing the link between infection enhancement and nuclear translocation of TFEB, we found that elevated concentrations of ridaforolimus, which resulted in increased infection, were also sufficient to inhibit TFEB phosphorylation." (PMID 36264642, 2022). "TFEB glycosylation has been documented to occur during host infection by Legionella pneumophila as a mechanism to ensure nutrient availability by activating catabolic pathways such as autophagy." (PMID 36231114, 2022). "TFEB depletion limited the ability of CVB3 to induce LC3 release during infection, which correlated with an overall decrease in EV-enclosed virus release." (PMID 35750662, 2022).